PEAR1 (platelet endothelial aggregation receptor 1)
Description:
Required for SVEP1-mediated platelet activation, via its interaction with SVEP1 and subsequent activation of AKT/mTOR signaling. May be involved in the early stages of hematopoiesis (By similarity).
Synonyms: MEGF12; JEDI; FLJ00193
Tractability: Antibody: UniProt places it where antibodies can reach, with high confidence; UniProt predicts a signal peptide or a membrane-spanning region; its Gene Ontology location is reachable by antibodies, with medium confidence.
Safety:
Unwanted effects reported when the protein is acted on. In parentheses: how it was acted on, where the effect was seen, and who reports it.
cardiovascular events (source: ClinPGx)
collagen induced platelet aggregation (source: ClinPGx)
myocardial infarction (source: ClinPGx)
platelet aggregation (source: ClinPGx)
Gene: Protein-coding gene on chromosome 1 (156,893,666 to 156,916,432, forward strand). Ensembl gene ENSG00000187800.
Subcellular location: Cell membrane; Cell projection, lamellipodium
Subcellular location (Human Protein Atlas): Cell Junctions; Centriolar satellite; Nucleoplasm
Gene Ontology:
Molecular function: protein binding; signaling receptor activity
Biological process: positive regulation of platelet activation; phosphatidylinositol 3-kinase/protein kinase B signal transduction; platelet aggregation
Cellular component: lamellipodium; plasma membrane; membrane; phagocytic cup
Genetic constraint (gnomAD): Loss-of-function variants: 113 observed, 125.75 expected, observed/expected ratio (o/e) 0.9, 90% interval 0.77 to 1.05. The upper end of that interval is the gene's LOEUF score, 1.05, which puts it in group 4 of 6, group 1 being the genes least tolerant of losing a copy. Missense variants: 1,408 observed, 1,387.5 expected, observed/expected ratio (o/e) 1.01, 90% interval 0.97 to 1.06. Synonymous variants: 565 observed, 529.38 expected, observed/expected ratio (o/e) 1.07, 90% interval 1 to 1.14.
Homologues: Orthologues: chimpanzee PEAR1 (99% identical), macaque PEAR1 (98% identical), pig PEAR1 (89% identical), dog PEAR1 (88% identical), guinea pig PEAR1 (85% identical), mouse Pear1 (84% identical), rat Pear1 (83% identical), rabbit PEAR1 (81% identical), Drosophila melanogaster NimA (11% identical). Paralogues in human: DLK1 (11% identical).
Diseases named in the same sentence as PEAR1 in open-access papers:
PEAR1 is named in the same sentence as 50 diseases in open-access papers, as found by Europe PMC text mining. Sharing a sentence is not in itself a finding about the gene and the disease. The quoted sentences say what the papers report.
Stroke (6 papers, 2018 to 2025). Sudden impairment of blood flow to a part of the brain due to occlusion or rupture of an artery to the brain. "This is a study that assessed the association of PEAR1 rs12041331 genetic polymorphism and the long-term cerebrovascular events, bleeding events, and clinical functions in patients with minor stroke or TIA." (PMID 34135847, 2021). "This study aims to investigate the effect of PEAR-1 rs12041331 polymorphism in stroke patients based on etiology classified by the Trial of Org 10172 in Acute Stroke Treatment (TOAST) and the association with the short-term functional outcomes after aspirin alone and DAPT." (PMID 34540909, 2021). "Research investigating the relationship between PEAR1 and stroke is scant, and the results remain elusive." (PMID 37891772, 2023). "Going forward, PEAR1 should be further investigated as a critical factor for managing treatment in stroke patients." (PMID 37891772, 2023). "The possible cell functional mechanisms that would link the PEAR1 genotype to stroke subtypes and stroke outcomes are further warranted to be investigated." (PMID 34540909, 2021). "Thus, it is possible that PEAR1 rs12041331 interacts with aspirin only in patients with specific stroke subtypes." (PMID 40640196, 2025). "Future studies analyzing polygenetic scores in different ethnic populations may enhance our understanding of the relationship between PEAR1 SNPs and clinical outcomes in stroke patients." (PMID 37891772, 2023). "In our study, we revealed the association between clinical parameters (age, NIHSS score, atrial fibrillation), as well as SNPs in the PTGS1, ADRA2A, TBXA2R and PEAR1 genes, and laboratory indicators of platelet activity in ischemic stroke patients taking aspirin for secondary stroke prevention." (PMID 36289824, 2022). "PEAR1 AA carrier with SAO stroke is most sensitive to aspirin therapy." (PMID 34540909, 2021). "Our data do provide robust evidence that genetic variation in PEAR1 rs12041331 does not contribute to atherothrombotic or bleeding risk in minor stroke and TIA patients treated with DAPT." (PMID 34135847, 2021). "At present, there are few studies on PEAR1 rs12041331 genotype in stroke." (PMID 34135847, 2021). "Patients on ASA with angiographically confirmed coronary artery disease (CAD) carrying PEAR1 rs2768759 SNPs were not at higher risk for death, MI, or stroke." (PMID 29867494, 2018). "However, the effects of PEAR1 rs12041331 might vary depending on the type of stroke and whether aspirin is being administered for primary or secondary stroke prevention." (PMID 40640196, 2025). "However, there has been no study on the relationship between PEAR1 polymorphism and the long-term cerebrovascular events in patients with minor stroke and TIA." (PMID 34135847, 2021). "Genetic variation in PEAR1 is thus considered a critical determinant of residual platelet function during aspirin treatment and might be a crucial determinant of residual platelet function during antiplatelet therapy, thereby affecting the clinical outcomes of stroke and TIA patients." (PMID 37891772, 2023). "As a preliminary observational study, we found no impact of PEAR1 rs12041331 on the prognosis of minor stroke and TIA." (PMID 34135847, 2021). "Platelet endothelial aggregation receptor 1 (PEAR1) rs12041331 has been recently associated with aspirin-alone or dual antiplatelet therapy (DAPT) response, although the association between rs12041331 and stroke outcome is not fully determined." (PMID 34540909, 2021). "However, patients carrying PEAR1 rs2768759 SNPs, diagnosed with angiographically confirmed CAD and treated with aspirin were not at higher risk for death, MI, or stroke." (PMID 29867494, 2018).
myocardial infarction (4 papers, 2015 to 2021). Gross necrosis of the myocardium, as a result of interruption of the blood supply to the area, as in coronary thrombosis. "Genome-wide association studies (GWAS) showed that PEAR1 gene variants are associated with greater platelet aggregability and it has been reported, that SNPs in PEAR1 are associated with an increased risk of myocardial infarction." (PMID 29867494, 2018). "We used linear mixed regression models (using age, gender, BMI, smoking, alcohol drinking, being a proband for family recruitment, being a member of myocardial infarction (MI) family as fixed effects, and family as a random effect) to evaluate associations between PEAR1 methylation and phenotypes." (PMID 31665082, 2019).
breast carcinoma (3 papers, 2024 to 2025). "Moreover, increased PEAR1 expression in patients with breast cancer was associated with poor overall survival, particularly in patients with TNBC." (PMID 39145451, 2024). "We also checked the effect of endothelium-specific loss of PEAR1 in a genetic mouse tumor model, the mouse mammary tumor virus (MMTV)-polyomavirus middle T antigen (PyMT) breast cancer model." (PMID 41185039, 2025). "Data pertaining to PEAR1 mRNA expression in various breast cancer cell lines were obtained from the open-access Human Protein Atlas, which revealed that PEAR1 was expressed at high levels predominantly in TNBC cells." (PMID 39145451, 2024). "The results revealed a notable increase in PEAR1 expression levels in breast cancer tissues compared with tumor-adjacent tissues (TATs)." (PMID 39145451, 2024). "In breast cancer, LOXL2‐activated PEAR1 phosphorylation facilitates metastasis by maintaining CD44 stability." (PMID 41395115, 2025). "To investigate the relationships between LOXL2, PEAR1, and PEAR1 Ser891 phosphorylation and CD44 in breast cancer, we subjected human TNBC samples to IHC." (PMID 39145451, 2024).
coronary artery disease (3 papers, 2014 to 2017). "Previous reports implicate PEAR1 rs12041331 as a variant influencing risk in patients with coronary heart disease." (PMID 28449647, 2017). "A common genetic variant in PEAR1 (rs12041331) reproducibly influenced platelet aggregation in aspirin-treated patients with coronary artery disease." (PMID 25360888, 2014).
thrombosis (3 papers, 2021 to 2024). "Sentinel variants at RGS18 and PEAR1 are associated with thrombosis risk and increased gastrointestinal bleeding risk, respectively." (PMID 34131117, 2021). "Sentinel variants at PEAR1 and RGS18 were associated with thrombosis risk through a whole genome sequencing, which provide insights regarding the mechanism by genetics may influence cardiovascular disease risk." (PMID 38166912, 2024).
Allergy (2 papers, 2023 to 2024). An allergy is an immune response or reaction to substances that are usually not harmful. "The unique relationship between Immunoglobulin E (IgE)-mediated allergy and cardiovascular disease was discovered to be PEAR1." (PMID 38299390, 2024). "The Kruskal-Wallis test revealed that the serum sIgE levels of allergy patients with AA (n=46), GA (n=136), and GG (n=101) genotypes of PEAR1 rs12041331 were statistically different (p =0.004)." (PMID 38299390, 2024). "The objective of this study is to investigate the potential association between gene polymorphisms in GP1BA rs6065, PEAR1 rs12041331, and PAI-1 rs1799762 and the levels of serum specific-IgE (sIgE) and blood eosinophils in Chinese patients with allergies." (PMID 38299390, 2024). "The HWE equilibrium law was followed by the frequency distributions of the following polymorphisms in allergy patients: CYSLTR1 rs320995, GSDMB rs7216389, GPIIIa rs5918, GP1BA rs6065, PEAR1 rs12041331, PAI-1 rs1799762, and TNF-α rs1800629 (p > .05)." (PMID 36911417, 2023). "The unique relationship between IgE-mediated allergy and cardiovascular disease was discovered to be PEAR1." (PMID 36911417, 2023). "Furthermore, our study highlights the potential significance of PEAR1 rs12041331 in the pathogenesis of allergic diseases." (PMID 38299390, 2024). "In conclusion, our study found that the GP1BA rs6065, PEAR1 rs12041331, and PAI-1 rs1799762 polymorphisms may be associated with the genetic susceptibility of serum sIgE or blood eosinophil in Chinese allergic disease patients." (PMID 38299390, 2024). "The GP1BA rs6065, PEAR1 rs12041331, and PAI-1 rs1799762 polymorphisms may be associated with the genetic susceptibility of serum sIgE or blood eosinophil in Chinese allergic disease patients." (PMID 38299390, 2024). "Based on the results of this study, it can be concluded that the GP1BA rs6065, PEAR1 rs12041331, and PAI-1 rs1799762 polymorphisms may be associated with the genetic susceptibility of serum sIgE or blood eosinophil in Chinese allergic disease patients." (PMID 38299390, 2024). "This study provides evidence of a potential correlation between genotypes of GP1BA rs6065, PEAR1 rs12041331, and PAI-1 rs1799762 and serum sIgE levels and blood eosinophil counts in Chinese allergy patients." (PMID 38299390, 2024). "Additionally, patients with the AA genotype of PEAR1 rs12041331 or 5G5G genotype of PAI-1 rs1799762 may have a lower serum sIgE level, which could be taken into consideration when interpreting allergy test results." (PMID 38299390, 2024).
colorectal cancer (2 papers, 2022 to 2024). A primary or metastatic malignant neoplasm that affects the colon or rectum. "In conclusion, our findings suggest that genetic and epigenetic variation in PEAR1 modulates the risk of colorectal cancer in white Flemish." (PMID 35390065, 2022). "Permutation analyses within the FLEMENGHO cohort supported the association colorectal cancer with PEAR1 gene variants." (PMID 35390065, 2022). "Our study confirmed our “a priori” hypothesis and to our knowledge is the first to relate in a randomly recruited population sample the risk of colorectal cancer to genetic and epigenetic variation in PEAR1." (PMID 35390065, 2022). "We therefore tested the association of incident colorectal cancer and genetic and epigenetic variability in PEAR1 among 2532 randomly recruited participants enrolled in the family-based Flemish Study on Environment, Genes and Health Outcomes (51.2% women; mean age 44.8 years)." (PMID 35390065, 2022). "We analysed the Flemish Study on Environment, Genes and Health Outcomes (FLEMENGHO) to investigate the “a priori” hypothesis of a possible association of colorectal cancer with genetic variation in PEAR1, as captured by rs12566888, which is in complete linkage disequilibrium with rs12041331." (PMID 35390065, 2022). "Platelet Endothelial Aggregation Receptor 1 (PEAR1) modulates angiogenesis and platelet contact-induced activation, which play a role in the pathogenesis of colorectal cancer." (PMID 35390065, 2022). "Further downstream, PEAR1 expression stimulates PTEN expression, a direct inhibitor of colorectal carcinogenesis and an inhibitor of angiogenesis sustaining colorectal cancer growth." (PMID 35390065, 2022). "Simtuzumab has shown limited efficacy in patients with pancreatic cancer or KRAS-mutant colorectal cancer, which may be due to the indirect and weak blocking effect of simtuzumab on the interaction of LOXL2 with PEAR1." (PMID 39145451, 2024).
endothelial dysfunction (2 papers, 2015 to 2017). In vascular diseases, endothelial dysfunction is a systemic pathological state of the endothelium (the inner lining of blood vessels) and can be broadly defined as an imbalance between vasodilating and vasoconstricting substances produced by (or acting on) the endothelium. "This is in apparent contradiction with several reports showing association of the rs12041331 A-allele with lower platelet function or PEAR1 expression or with endothelial dysfunction." (PMID 28449647, 2017). "Preeclampsia, a condition characterized by high blood pressure and endothelial dysfunction, was also predicted to be influenced by PEAR1." (PMID 26406321, 2015).
pulmonary fibrosis (2 papers, 2015 to 2022). Chronic progressive interstitial lung disorder characterized by the replacement of the lung tissue by connective tissue, leading to progressive dyspnea, respiratory failure, or right heart failure. "Furthermore, several genes that were significantly co-expressed with PEAR1 have also been previously implicated in endothelial-related pathological conditions including pulmonary fibrosis (CTGF) and hemorrhagic telangiectasia (ACVRL1 and ENG)." (PMID 26406321, 2015). "Intratracheal aerosolization of monoclonal antibodies activating PEAR1 greatly ameliorates pulmonary fibrosis in both WT and Pear1-humanized mice, significantly improving their survival rate." (PMID 36402779, 2022). "Mesenchyme-specific Pear1 deficiency aggravates bleomycin-induced pulmonary fibrosis, confirming that PEAR1 potentially modulates pulmonary fibrosis progression via regulation of mesenchymal cell function." (PMID 36402779, 2022). "Here we show that platelet endothelial aggregation receptor 1 (PEAR1) in fibroblasts may serve as a target for pulmonary fibrosis therapy." (PMID 36402779, 2022). "Here, the authors reveal a novel role of PEAR1 in fibroblast activation and demonstrate that activating PEAR1 by monoclonal antibodies might be a promising therapeutic approach for pulmonary fibrosis." (PMID 36402779, 2022). "The role of PEAR1 in fibrosis was then evaluated by an amiodarone-induced pulmonary fibrosis model." (PMID 36402779, 2022).
transient ischemic attack (2 papers, 2021 to 2023). A brief attack (from a few minutes to an hour) of cerebral dysfunction of vascular origin, with no persistent neurological deficit. "In this study, we explored the relationship between the platelet endothelial aggregation receptor 1 (PEAR1) polymorphisms, platelet reactivity, and clinical outcomes in patients with minor stroke or transient ischemic attack (TIA)." (PMID 37891772, 2023). "Here we assess the clinical relevance of PEAR1 rs12041331 in acute minor ischemic stroke (AMIS) and transient ischemic attack (TIA) Chinese patients treated with dual antiplatelet therapy (DAPT)." (PMID 34135847, 2021).
acute myeloid leukemia (1 paper, 2025). Acute myeloid leukemia (AML) is a group of neoplasms arising from precursor cells committed to the myeloid cell-line differentiation. "In triple-negative cancer cells, PEAR1 has been shown to promote metastasis, and in acute myeloid leukemia cells its expression is correlated with poor progrnosis." (PMID 41185039, 2025).
asthma (1 paper, 2024). "For example, the glycoprotein Ib alpha gene (GP1BA) has been linked to severe, treatment-refractory asthma, while platelet endothelial aggregation receptor 1 (PEAR1) has been found to be highly correlated with cardiovascular illness." (PMID 38299390, 2024).
breast tumor (1 paper, 2024). "To reveal the clinical relevance of PEAR1 expression, we performed microarray analysis of human breast tumor tissues alongside adjacent nontumor tissues using IHC staining of PEAR1." (PMID 39145451, 2024).
COVID-19 (1 paper, 2021). A disease caused by infection with severe acute respiratory syndrome coronavirus 2. "After TRAP stimulation, platelets of COVID-19 patients showed significantly higher levels of the collagen receptor GPVI, whereas the receptor PEAR1 showed lower levels in COVID-19." (PMID 33414384, 2021).
diabetic nephropathy (1 paper, 2015). "Intriguingly, other diseases predicted to be related to PEAR1 included several types of cancer (e.g. colorectal, pancreatic, and non-small cell lung carcinoma), osteoarthritis, and diabetic nephropathy." (PMID 26406321, 2015). "While there is currently no available data suggesting a relationship between PEAR1 and osteoarthritis, diabetic nephropathy, aortic aneurisms, or cancer risk, it is interesting to speculate given the role of the TGF-β signaling system in the progression of these disorders." (PMID 26406321, 2015).
IgA nephropathy (1 paper, 2026). "Transcriptomic-wide MR identified candidate genes across GN subtypes: RECQL, BRSK2, and MGP in acute GN; AFM, CFHR5, and EPHB2 in chronic GN; IL6R, MBL2, and PRSS3 in IgA nephropathy; and TIMP4, HCK, and PEAR1 in membranous nephropathy." (PMID 41990104, 2026).
Insulin resistance (1 paper, 2025). Increased resistance towards insulin, that is, diminished effectiveness of insulin in reducing blood glucose levels. "For instance, subsets with severe insulin resistance or genetic polymorphisms in COX-1/PEAR1 may exhibit distinct pharmacodynamic profiles, diluting the independent effect of individual factors in logistic regression." (PMID 40934219, 2025).
Kawasaki disease (1 paper, 2021). A rare inflammatory disease characterized by an acute febrile, systemic, self-limiting, medium-vessel vasculitis primarily affecting children. "A PEAR1 polymorphism has previously been associated with coronary artery aneurism in Kawasaki disease and ERAP1 was identified as a susceptibility locus for Kawasaki disease in a Chinese population." (PMID 34531865, 2021). "Only P5 had variants in genes (PEAR1, ERAP1) previously linked to Kawasaki disease." (PMID 34531865, 2021). "A different PEAR1 variant than the one identified in the present study has previously been associated with risk of coronary artery aneurism in Kawasaki disease, whereas ERAP1 was identified as a novel susceptibility locus for Kawasaki disease in a genome-wide association study." (PMID 34531865, 2021).
lentivirus infection (1 paper, 2024). Virus diseases caused by the Lentivirus genus. "To evaluate the role of PEAR1 in TNBC cells, we generated stable PEAR1-knockdown (shPEAR1) and PEAR1-overexpression (oe-PEAR1) MDA-MB-231 and SUM159 cell lines using lentivirus infection, which we confirmed with quantitative real-time PCR (RT-qPCR) and Western blotting." (PMID 39145451, 2024).